IL6 (interleukin 6)
Diseases named in the same sentence as IL6 in open-access papers (continued):
Sharing a sentence is not in itself a finding about the gene and the disease.
Obesity (continued). "It is reported that alone acupuncture on the ST36 acupoint can decrease the leukocyte infiltration to adipose tissue and attenuates inflammatory response by reducing serum levels of TNF-α, IL-6, and IL-1 in HFD-induced obesity rats." (PMID 32724821, 2020). "An observational trial confirmed that people with obesity have higher levels of leptin, adipsin, retinol binding protein-4 (RBP-4), IL-6, high sensitivity-C reactive protein (Hs-CRP) and lower levels of adiponectin and visfatin as compared to lean people." (PMID 33511131, 2020). "IL-6 and TNF-α enhance the hepatic production of C-creative protein (CRP), which is increased under conditions of obesity." (PMID 32948162, 2020). "The intensive secretion of IL-6, TNF-α, and MCP-1 sustains the unbalanced inflammation on individuals with obesity." (PMID 32849309, 2020). "The higher immunoreaction, shown for IL-6 and TNF-α in the older obese rats compared to lean, suggested an inflammatory process at the cardiovascular level due to obesity." (PMID 32188150, 2020). "We assessed the levels of the cytokines IL-1β, IL-6, and TNF-α as well as the chemokine RANTES since previous studies have shown that they are elevated in liver of diet-induced rodent models of obesity and contribute to NAFLD pathogenesis." (PMID 32751772, 2020). "In obesity, adipocytes secrete proinflammatory cytokines (TNF-α and IL-6), also known as adipokines, into the circulation." (PMID 33425000, 2020). "Individuals with obesity present high concentrations of CRP, an acute phase inflammatory marker mainly produced in the liver, and this process is regulated predominately by IL-6." (PMID 32893859, 2020). "Obesity is a chronic low-grade inflammation, and the concentrations of resistin, leptin, and IL-1β, as well as TNF-α and IL-6, in peripheral blood of obese patients were significantly increased." (PMID 32104715, 2020). "Particularly, we confirmed that the extent of upregulation of three genes including IL-6, IL-1β, and TNF-α, i.e., the three most studied inflammatory genes related to obesity, was significantly greater in ‘Lean_Ag-DEGs’ than in ‘Obese_Ag-DEGs’ (P < 0.01)." (PMID 33183332, 2020). "Chronic inflammation mediated by HFHSD-induced obesity is marked by increased pro-inflammatory cytokines such as TNF-α, IL-1β, and IL-6 in circulation." (PMID 32143330, 2020). "Although physiological and positive effects of IL6 action have also been reported (increased satiety, leptin release, IL4R expression in macrophages), the aberrant IL6 expression in diet-induced obesity results in chronic activation of its inflammatory axis." (PMID 32785109, 2020). "In the liver, EPO inhibited gluconeogenesis, attenuated obesity-related inflammatory cytokine expression and production of TNF-α and IL-6, reduced the activation of NFκB and inflammatory signaling, and enhanced insulin-related PI3K signaling." (PMID 33330462, 2020). "During obesity the phenotypic deviation of M2 to M1 macrophages in adipose tissue increases the production of proinflammatory cytokines such as TNF-α and IL-6, which inhibit the insulin receptor signaling." (PMID 32774333, 2020). "Numerous studies have demonstrated that HFD feeding and obesity contribute to increases in circulating cytokines and acute phase proteins such as CRP, TNFα, and IL-6." (PMID 32823541, 2020). "On the other hand, the reverse situation also appears to be true, since it was observed that insulin and obesity stimulates the gene expression of TNF-α and IL-6 in adipose tissue." (PMID 32187268, 2020). "Among cytokines, the most related to obesity and insulin resistance are tumor necrosis factor-α (TNF-α) and interleukin-6 (IL-6)." (PMID 33167421, 2020). "In this review, we have summarized the current knowledge about gp130 cytokines, including IL-6, LIF, CNTF, CT-1, and OSM, in adipocyte biology and metabolic activities in conditions such as obesity and type 2 diabetes." (PMID 31275060, 2019).
Obesity (continued). "Adipose tissue of individuals with obesity exhibit elevated expression of TNF-α, IL-6, CCL2, FFAs, and IL-8 when compared with normo-weight controls." (PMID 31443599, 2019). "The immune cell infiltration of adipose tissue increased production of pro-inflammatory cytokines (e.g., TNF-α, IL-1, IL-6, and IL-8) that were reported to be associated with increased risk of nephritis in HSP, which may be a potential mechanism to explain the relationship between obesity and HSPN." (PMID 31735105, 2019). "Of note, it has also been demonstrated the inhibitory effects of sweet cherry anthocyanins on obesity development in HFD fed mice, by slowing down TNFα and IL-6 levels." (PMID 31130968, 2019). "Macrophages represent a large proportion of the immune cell population in PVAT, and in obesity macrophages are the main source of TNF-α and IL-6." (PMID 30747398, 2019). "Both IL-6 and TNF-α levels can be increased in obesity, and both cytokines can cross the blood–brain barrier by a saturable transport mechanism." (PMID 31739649, 2019). "In the obese state, necrotic adipocyte recruits macrophages to secret pro-inflammatory cytokines, such as TNF-α, IL-1β, IL-6, MCP-1, which potentially arouses obesity-related insulin resistance." (PMID 31548850, 2019). "Taken together, these results suggest that IL-6 and CCL-2 are the inflammatory mediators linking obesity with enhanced effector Th responses and EAE." (PMID 31507583, 2019). "In this study, we demonstrated that FGF-1 treatment significantly ameliorated obesity and TNF-α-induced stimulated cytokine secretion such as TNF-α and IL-6 as well as enhancing anti-inflammatory." (PMID 31866871, 2019). "Significant biomarkers of inflammation (hsCRP, IL-6, and TNF-alpha) and endothelial dysfunction (sICAM-1 and sVCAM-1) are present in young children with obesity." (PMID 30625218, 2019). "One characteristic of hypoxia in obesity is an increase in expression of pro-inflammatory cytokines such as tumour necrosis factor alpha (TNF-α) and interleukin-6 (IL-6)." (PMID 30747398, 2019). "Mechanistically, obesity induces a pro-inflammatory microenvironment featured by elevated CCL-2 and IL-6 levels, and promotes the proliferation and activation of encephalitogenic T cells into the CNS." (PMID 31507583, 2019). "This was manifested by a reduction in both the expression and the release of proinflammatory cytokines, which are key in the development of obesity-related complications, such as TNF-α, IL-1β, and IL-6." (PMID 31438646, 2019). "In this study, with the reduction of obesity, HFD+SC06 also significantly decreased the concentration of IL-6 and TNF-α compared to that of HFD." (PMID 31191487, 2019). "We found that the levels of MCP‐1, IL‐6 and TNF‐α in obese mice (Obesity) were 1.51, 1.75 and 1.43‐fold higher than those in normal control mice (Control), respectively." (PMID 31270932, 2019). "Obesity-induced chronic inflammation leads to overexpression of TNFα (tumor necrosis factor alpha), IL6 (interleukin 6), IL18 (interleukin 18), and other pro-inflammatory cytokines that are also known to inhibit adiponectin." (PMID 31121868, 2019). "Increased pro-inflammatory cytokines such as TNF-α, IL-1, IL-6, and PGE2 are hallmarks of obesity and obesity-induced breast cancer development." (PMID 31616626, 2019). "Taken together, these data suggest that obesity promotes the pathogenesis of EAE through CCL-2 and IL-6 mediated CNS inflammation." (PMID 31507583, 2019). "On the other hand, activation of TLR-4 in adipose tissues occurs through interactions with gut microbiota LPS or adipocyte lipolysis-released free fatty acids, which can induce the secretion of inflammatory adipocytokines (i.e., IL-6 and TNF) in obesity." (PMID 31632356, 2019). "Many previous studies have indicated that IL-6 and TNF-α are involved in obesity-related diseases like atherosclerosis and insulin resistance." (PMID 30854010, 2019).
Obesity (continued). "We observed enhanced IL-6 and CCL-2 production in obesity animals, which derived from adipose tissue M1 macrophages and adipocytes." (PMID 31507583, 2019). "The current study demonstrated that energy-restricted and surgical strategies of weight loss induced changes in levels of circulating myokines such as IL-6, IL-8, MMP2, and irisin in patients with obesity." (PMID 31590286, 2019). "In vitro treatment of KCs with FFAs (e.g., palmitate) promotes activation and secretion of inflammatory cytokines (e.g., IL-6, TNF, IL-1β) while KC depletion in vivo protects from obesity-driven hepatic steatosis." (PMID 31921154, 2019). "The expanded mass of dysfunctional adipose tissue in obesity is reportedly a source of several proinflammatory molecules, such as TNF-α, IL-6 and MCP-1, which are predominantly produced by the stromal-vascular cells (SVCs) within adipose tissue." (PMID 30813240, 2019). "In adipose tissues in obesity, expressions of pro-inflammatory cytokines such as MCP-1, IL-6, TNFα, and IL-1β in macrophages and/or adipocytes have been reported to increase." (PMID 31509948, 2019). "In addition, obesity causes lipid accumulation, activates JNK and NF-κB signaling pathways, and might subsequently increase the production of pro-inflammatory cytokines such as TNF-α and IL-6." (PMID 31866871, 2019). "Osteopontin expression in human macrophages is also upregulated by a variety of pro-inflammatory mediators, including TNF-α, IL-6, and oxidized LDL, known to be elevated in obesity, type 2 diabetes, and cardiovascular disease." (PMID 31694146, 2019). "In all participants with obesity (group 2 and 3), correlations between serum biomarkers (hs-CRP, IL-6, TNF-α, M30 level, insulin resistance) and LV diastolic function parameters were analyzed by multivariate regression." (PMID 31120986, 2019). "In the present study, significant correlation was observed between serum IL-6 and TNF-α and this correlation remained significant even after controlling for the possible confounders, such as age, sex, BP and obesity markers." (PMID 30635365, 2019). "Obesity is known to feature a chronic inflammatory process, with increased levels of proinflammatory cytokines (TNF-α, IL-6, IL-12), generation of reactive oxygen species, and greater differentiation of activated macrophages into the M1 phenotype." (PMID 31138279, 2019). "TLR2/4 activation causes a proinflammatory response in autoimmune diseases and contributes to an obesity-induced inflammatory response by increasing TNF-a and IL-6 levels in RA and TNF-a, IL-6, IL-23, and IL-10 levels in SLE." (PMID 31788032, 2019). "In obese subjects (n = 173), the degree of obesity and BMD were related to IL-6 levels (in males), osteocalcin (in females), C-reactive protein (CRP), and leptin indicating that adiposity and systemic inflammation are associated with low BMD." (PMID 30792697, 2019). "Pro-inflammatory macrophages play an important role in adipose tissue inflammation during obesity, as they overexpress genes important in macrophage migration and phagocytosis including TNF, iNOS and IL-6." (PMID 30096208, 2018). "As noted in the obesity section, increased BMI or obesity is related to greater systemic inflammation (e.g., CRP, IL-6, and TNF-α levels)." (PMID 30538987, 2018). "IL-6 and TNF-α are the 2 best-studied cytokines in obesity and have been consistently found to be increased in the serum, white adipose tissue, or both in obese subjects." (PMID 29593725, 2018). "Hypertrophic adipocytes can secrete various pro-inflammatory cytokines such as TNF-α and IL-6, and the level of pro-inflammatory factor MCP-1 is believed to be significantly increased during the development and progression of obesity." (PMID 30347741, 2018). "Mice over-expressing human IL-6 have less visceral fat when fed a normal diet and are free from high-fat-diet (HFD)-induced obesity." (PMID 30134607, 2018).
Obesity (continued). "In established obesity, omentectomy eliminates the omental production of inhibitors of the leptin and insulin effects, particularly CRP and IL-6." (PMID 29367725, 2018). "An anti-inflammatory effect of apigenin was previously reported in a murine model of HFD-induced obesity, where its administration reduced plasma levels of MCP-1, TNF and IL-6." (PMID 29641549, 2018). "Obesity is thought to induce a proinflammatory state and adipose tissue releases signals including leptin, TNF-alpha and IL-6." (PMID 30631374, 2018). "IL-6 and TNF-α govern the chronic low-lying systemic inflammation characteristic of obesity by paracrine inhibition of the anti-inflammatory adipokine “adiponectin”." (PMID 29486749, 2018). "Results showed improvements in obesity-related inflammatory profiles after following plant-based diets: CRP (−0.55 mg/L), IL-6 (−0.25 ng/L), and sICAM-1 (−25.07 ng/mL)." (PMID 30544955, 2018). "IL-6 and TNF-α are two main proinflammatory cytokines that are significantly increased in obesity patients with excessive WAT." (PMID 30013512, 2018). "Taken together, there are discrepancies among studies in terms of the effects of IL-6 on obesity and NAFLD, and further research is required to clarify the effects of IL-6 on NAFLD as a myokine and as an inflammatory cytokine." (PMID 30374329, 2018). "Consistently, we found that the serum IL-6 levels were significantly elevated (p < 0.05) and positively correlated with CCRK protein expression in both dietary obesity-induced NASH and HCC models (p < 0.01)." (PMID 30523261, 2018). "In terms of cytokines, plasma IL-6 (p < 0.01) and CRP (p < 0.0001) were significantly elevated with pregravid obesity." (PMID 30131724, 2018). "Recent studies have confirmed that obesity is a state of chronic inflammation that is characterised by increased concentrations of tumour necrosis factor-alpha (TNF-α), interleukin-6 (IL-6) and other inflammatory markers." (PMID 30914847, 2018). "In obesity, the hypertrophied adipocytes produce proinflammatory cytokines including MCP-1, TNF-α and IL-6." (PMID 29473848, 2018). "In obesity, increased AT IL6, IL6R, and SOCS3 mRNA expression was observed, however, unchanged AT IL6, IL6R and IL6ST expression was also reported." (PMID 29737494, 2018). "Obesity, impaired IS or T2DM are characterized by low-grade inflammation frequently assessed by CRP as well as interleukin 6 (IL-6) or tumor necrosis factor alpha (TNFα)." (PMID 30294302, 2018). "This study also identified IL-6 and IL-10 as markers of TLR4 activation in HCC and subjects with NAFLD and obesity as the target population who would benefit from TLR4 inhibition treatment for HCC chemoprevention." (PMID 30034633, 2018). "It was observed that IL-6 and TNF-α inhibit the expression of adiponectin, which is an adipokine, inversely correlated with the obesity, its increase plays an important anti-inflammatory role." (PMID 30201891, 2018). "Third, vanillin reduced elevated levels of inflammatory factors including LPS, IL-6, and TNF-α in plasma and liver tissue resulting from obesity." (PMID 30483238, 2018). "Given that IL-6 is pro-inflammatory, it is widely accepted that like TNF-α, IL-6 negatively impacts obesity-induced IR." (PMID 31565650, 2018). "There was a significant correlation between hs-CRP, IL-6 and TNF-α with measures of obesity such as BMI and WC." (PMID 29099041, 2017). "Obesity also augmented ozone-induced increases in BAL CXCL1 and IL-6, and in BAL type 2 cytokines, whereas anti-ST2 treatment reduced these cytokines." (PMID 27472835, 2017). "During obesity, leukocyte infiltration in WAT, composed mainly by macrophages, enhances TNF-α and IL-6 production, to initiate and maintain the inflammatory process." (PMID 29220408, 2017).
Obesity (continued). "While an increasing number of adipokines are implicated in the development of the obese phenotype, the focus of this review will include MCP-1, IL-6, TNF-α, IL-1β, leptin and adiponectin as the key mediators of AT inflammation and dysfunction in obesity." (PMID 29186929, 2017). "IL-6 and TNF-α are pro-inflammatory cytokines and were overproduced during obesity, thereby contributing to the pathogenesis of insulin resistance." (PMID 28893239, 2017). "At least 24 typical inflammatory mediators such as leptin, resistin, IL-6, TNF, and chemokines, among others (e.g., C-reactive protein, haptoglobin, and amyloid A) are upregulated during obesity." (PMID 28293269, 2017). "CD14+CD16+ monocytes are potent secretors of IL-1, IL-6 and TNF-α, and expanded CD14+CD16+ monocyte populations are found in inflammatory disease states including atherosclerosis, obesity and rheumatoid arthritis." (PMID 28494757, 2017). "In obesity, the enlarged adipose tissue is infiltrated by a large number of macrophages, due to which production of pro-inflammatory adipokines such as MCP-1, IL-6, and TNFα increases." (PMID 28248545, 2017). "Adiponectin levels are inadequate in obesity, while leptin (an inflammatory lipokine) augments TNF-α and IL-6 production." (PMID 29064461, 2017). "Thus, IL-6-mediated adipocyte dysfunction and adipokine secretion may potentiate the cross-talk between adipocytes and immune cells within AT to contribute to the maintenance of chronic low-grade inflammation in obesity." (PMID 29186929, 2017). "Inflammatory marker IL-6, TNF-alpha and MCP-1 levels in fasting plasma were similar between GNB3-T/+ and WT mice prior to and during obesity." (PMID 29206867, 2017). "There is substantive evidence supporting the notion that obesity is correlated with a chronic inflammatory response based on the identification of abnormal cytokines such as TNF-α and IL-6, along with the activation of pro-inflammatory signaling pathways." (PMID 29354072, 2017). "In particular, in obesity, adipocyte JNK activation was tied in mice to NAFLD by regulating IL-6 as an endocrine mediator in the fat-liver axis." (PMID 28360082, 2017). "Cross-sectional studies have shown that many individuals with obesity and/or MDD have elevated levels of cytokines, including interleukin (IL)-6, tumor necrosis factor (TNF)-α and C-reactive protein (CRP)." (PMID 29176959, 2017). "A previous study reported that obesity induced by a high fat diet (HFD) in mice leads to increased cardiac and serum IL-6 levels, along with myocardial disruption of glucose metabolism." (PMID 29201273, 2017). "In this study, we evaluated the role of cytokines in T2DM and obesity by measuring plasma TNF-α, IL-6, and IL-10 levels." (PMID 28225860, 2017). "On the other hand, maternal obesity compounded with the Mc4r KO genotype had decreased α-SMA (−0.73-fold, p < 0.01), TNF-α (−0.54-fold, p < 0.05), and IL6 (−0.56-fold, p < 0.05) hepatic mRNA levels in the offspring." (PMID 28930194, 2017). "Previous studies have demonstrated that PS and obesity share common inflammatory mediators such as CRP and IL-6." (PMID 28947858, 2017). "Obesity induces a switch from anti-inflammatory M2 ATM towards pro-inflammatory M1 ATM which secrete pro-inflammatory cytokines, such as TNF-α, IL-6, IL1-β, IL-12, IL-23, and leukocyte-attracting chemokines, such as IL-8, Rantes, MIP-1α and MIP-1β." (PMID 28708082, 2017). "The levels of inflammatory cytokines, like interleukin-6 (IL-6) and tumor necrosis factor-alpha (TNF-α), as well as C-reactive protein (CRP) are elevated in obesity and insulin-resistant states." (PMID 28836404, 2017). "Higher IL-6 levels were found in T2DM patients and our results suggest that obesity acts synergistically with T2DM by modulating the increase of this cytokine." (PMID 28225860, 2017). "In general, proinflammatory plasma markers such as TNF-α, IL-6, and MCP-1 are present in an early inflammatory stage of obesity." (PMID 27869712, 2016).